OCRL (OCRL inositol polyphosphate-5-phosphatase)
Description:
Catalyzes the hydrolysis of the 5-position phosphate of phosphatidylinositol 4,5-bisphosphate (PtdIns(4,5)P2) and phosphatidylinositol-3,4,5-bisphosphate (PtdIns(3,4,5)P3), with the greatest catalytic activity towards PtdIns(4,5)P2. Also, is able to hydrolyze the 5-phosphate of inositol 1,4,5-trisphosphate and of inositol 1,3,4,5-tetrakisphosphate. Regulates traffic in the endosomal pathway by regulating the specific pool of phosphatidylinositol 4,5-bisphosphate that is associated with endosomes. Involved in primary cilia assembly. Acts as a regulator of phagocytosis, hydrolyzing PtdIns(4,5)P2 to promote phagosome closure, through attenuation of PI3K signaling.
Synonyms: OCRL-1; OCRL1; Dent-2; DENT2; LOCR
Tractability: Small molecule: a structure with a bound ligand is known; it has a binding pocket of medium quality. Antibody: its Gene Ontology location is reachable by antibodies, with high confidence. PROTAC: ubiquitination databases record sites on it; its protein half-life has been measured.
Gene: Protein-coding gene on chromosome X (129,539,849 to 129,592,561, forward strand). Ensembl gene ENSG00000122126.
Subcellular location: Cytoplasmic vesicle, phagosome membrane; Early endosome membrane; Membrane, clathrin-coated pit; Cell projection, cilium, photoreceptor outer segment; Cell projection, cilium; Cytoplasmic vesicle; Endosome; Golgi apparatus, trans-Golgi network; Lysosome
Subcellular location (Human Protein Atlas): Microtubules; Primary cilium; Basal body; Centriolar satellite; Cytosol
Pathways (Reactome):
Metabolism: Synthesis of IP2, IP, and Ins in the cytosol; Synthesis of IP3 and IP4 in the cytosol; Synthesis of PIPs at the Golgi membrane; Synthesis of PIPs at the plasma membrane
Signal Transduction: RAC3 GTPase cycle; RHOJ GTPase cycle
Vesicle-mediated transport: Clathrin-mediated endocytosis; Golgi Associated Vesicle Biogenesis
Gene Ontology:
Molecular function: GTPase activator activity; inositol phosphate phosphatase activity; inositol-1,3,4,5-tetrakisphosphate 5-phosphatase activity; inositol-1,4,5-trisphosphate 5-phosphatase activity; phosphatidylinositol-3,4,5-trisphosphate 5-phosphatase activity; phosphatidylinositol-4,5-bisphosphate 5-phosphatase activity; protein binding; small GTPase binding; phosphatidylinositol phosphate 4-phosphatase activity; phosphatidylinositol-3,5-bisphosphate 5-phosphatase activity; inositol-polyphosphate 5-phosphatase activity; phosphatase activity; phosphatidylinositol bisphosphate phosphatase activity; phosphatidylinositol phosphate 5-phosphatase activity
Biological process: cilium assembly; inositol phosphate metabolic process; lipid metabolic process; membrane organization; phosphatidylinositol biosynthetic process; phosphatidylinositol dephosphorylation; phosphatidylinositol metabolic process; phosphatidylinositol-3-phosphate biosynthetic process; signal transduction
Cellular component: cilium; clathrin-coated vesicle; cytoplasm; early endosome; early endosome membrane; endosome; lysosome; nucleus; photoreceptor outer segment; plasma membrane; trans-Golgi network; cytoplasmic vesicle; cytosol; Golgi stack; Golgi-associated vesicle; membrane; neuron projection; clathrin-coated pit; Golgi apparatus; phagocytic vesicle membrane
Gene-disease validity (ClinGen):
ClinGen rates the evidence that OCRL causes each of these diseases.
oculocerebrorenal syndrome (X-linked): Definitive. Oculocerebrorenal syndrome of Lowe (OCRL) is a multisystem disorder characterized by congenital cataracts, glaucoma, intellectual disabilities, postnatal growth retardation and renal tubular dysfunction with chronic renal failure.
Homologues: Orthologues: chimpanzee OCRL (99% identical), macaque OCRL (99% identical), guinea pig OCRL (96% identical), rabbit OCRL (95% identical), pig OCRL (95% identical), rat Ocrl (93% identical), mouse Ocrl (91% identical), tropical clawed frog ocrl (73% identical), zebrafish ocrl (62% identical), Drosophila melanogaster Synj (20% identical), Caenorhabditis elegans unc-26 (18% identical), Drosophila melanogaster CG9784 (15% identical), and 3 more. Paralogues in human: INPP5B (45% identical), SYNJ2 (23% identical), SYNJ1 (21% identical), INPP5D (20% identical), INPP5J (20% identical), INPPL1 (19% identical), INPP5F (15% identical), INPP5E (14% identical), INPP5K (13% identical), FIG4 (12% identical), SACM1L (9% identical), SH2D1B (3% identical), and 1 more.
Diseases named in the same sentence as OCRL in open-access papers:
OCRL is named in the same sentence as 83 diseases in open-access papers, as found by Europe PMC text mining. Sharing a sentence is not in itself a finding about the gene and the disease. The quoted sentences say what the papers report.
Lowe syndrome (106 papers, 2009 to 2026). "Splicing variants in OCRL exons 1 to 7 resulted in Dent disease-2, and in exons 9 to 24 resulted in Lowe syndrome." (PMID 40485688, 2025). "This led to the understanding that there is an important splice variant (i.e., OCRL isoform) that maintains OCRL function, and this isoform rescues Dent disease-2 from systemic OCRL dysfunction in Lowe syndrome." (PMID 40163114, 2025). "Loss of OCRL leads to defective neuronal excitability in Lowe Syndrome patient iPSC-derived neurons and increased GFAP in mature forebrain cortical neural cultures and brain organoids." (PMID 41219536, 2025). "Studies in these model systems are leading to new insights about normal Ocrl1 functions/interactions, changes in the cellular milieu induced by OCRL variants and the potential contribution of cell phenotype to Lowe syndrome clinical phenotypes." (PMID 41278199, 2025). "Lowe syndrome and Dent-2 disease are caused by mutations in the gene encoding OCRL, an inositol 5-phosphatase." (PMID 40778266, 2025). "Reports of the same mutation causing either Dent 2 or Lowe syndrome with different severity underscore the difficulty in using the OCRL genotype to predict clinical phenotype or severity." (PMID 41278199, 2025). "Mutations of the OCRL gene cause faulty functioning of the inositol polyphosphate 5-phosphatase (OCRL-1) protein, causing the oculocerebrorenal symptoms visualized in Lowe syndrome." (PMID 40428338, 2025). "Muscle biopsies in 3 Lowe syndrome patients and one Dent 2 patient showed primary myopathy suggesting direct muscle injury in at least some of the patients with OCRL variants." (PMID 41278199, 2025). "The same OCRL gene variant is known to cause clinical features of Lowe syndrome in one patient and of Dent 2 in another and to manifest different features or different severity of features between families and even within affected boys of the same family." (PMID 41278199, 2025). "Loss-of-function mutations in OCRL cause Lowe syndrome, a rare X-linked recessive disorder characterized by renal tubular dysfunction, developmental delay, intellectual disability, and congenital cataracts." (PMID 40565289, 2025). "Lowe syndrome was discovered in the 1950’s, but it was not until the early 1990’s that the causative gene was identified as OCRL, which encodes an inositol 5-phosphatase that has been extensively studied since, and which I describe further below." (PMID 40778266, 2025). "Meanwhile, OCRL is the causative gene of Dent disease-2 and encodes phosphatidylinositol 4,5-bisphosphate 5-phosphatase, and its variants are also associated with Lowe syndrome." (PMID 40163114, 2025). "Over recent years our understanding of OCRL cellular function has improved markedly, and animal models have been developed to investigate the mechanisms underlying Lowe syndrome and Dent-2 disease." (PMID 40778266, 2025). "Lowe syndrome (LS), a rare X-linked disorder caused by mutations in OCRL, with an estimated prevalence of 1 in 500,000 people." (PMID 41219536, 2025). "Lowe syndrome is an X-linked disorder caused by mutations of the OCRL gene which encodes the enzyme inositol polyphosphate-5-phosphatase OCRL (Ocrl1) and is expressed in almost all body cells." (PMID 41278199, 2025). "Used alongside other models, including the Lowe syndrome mouse, and patient-derived OCRL-deficient iPSC cells that can be cultured into brain or kidney organoids, it represents a valuable model going forwards." (PMID 40778266, 2025). "In case gs6 with X-linked recessive Lowe syndrome caused by OCRL, Lowe syndrome, a severe disorder, is characterized by congenital cataracts, mental disabilities, and hypotonia." (PMID 38785568, 2024). "Lowe syndrome, an X-linked disorder caused by OCRL mutations, leads to neurodevelopmental delays and other issues." (PMID 39553960, 2024).
Lowe syndrome (continued). "A successful exon-skipping strategy has been developed to restore significant levels of OCRL mRNA and protein in a Lowe syndrome patient with an intronic mutation." (PMID 38785568, 2024). "LS 100 is a 17-year-old with Lowe syndrome who was delivered after a 36-week pregnancy and diagnosed by genetic sequencing of OCRL mutations." (PMID 39553960, 2024). "Two types of Dent disease have been identified: type 1 caused by mutations in CLCN5 and type 2 caused by specific mutations in OCRL (other OCRL mutations cause Lowe syndrome) that manifests with a Dent-like phenotype." (PMID 38873575, 2024). "Some patients with OCRL variants present with Dent disease type 2, which is thought to be a milder presentation of classical Lowe syndrome." (PMID 38292052, 2023). "Mutations in PI 5-phosphatase, OCRL are associated with oculocerebrorenal syndrome of Lowe, a ciliopathy." (PMID 37007713, 2023). "OCRL mutations are identified as causative of two human diseases: oculocerebrorenal syndrome of Lowe (OCRL), also called Lowe syndrome, and Dent-2 disease." (PMID 36547473, 2022). "Oculocerebrorenal dystrophy, also known as Lowe syndrome, is caused by mutation in the OCRL gene that encodes for inositol 5-phosphatase." (PMID 36552741, 2022). "Recently, a large international study of OCRL variants widened the range of exons leading to Dent-2 disease phenotype demonstrating that mutations in Lowe syndrome are located among exons 8 and 24, while exons 4–15 are affected in Dent-2 disease." (PMID 35919034, 2022). "Truncating mutations of the OCRL gene were more common in patients with Lowe syndrome than in Dent-2 disease, while mutation is more likely located at exon 2–12 in Dent-2 disease than that in Lowe syndrome." (PMID 35919034, 2022). "Another gene product involved in proximal tubule endocytosis is OCRL, and pathogenic variants cause Lowe syndrome, which is associated with low molecular weight proteinuria 20,21." (PMID 35716957, 2022). "This syndrome shares many similar features to classical ciliopathy syndromes and is especially close to the Lowe syndrome caused by mutations in the PI 5-phosphatase OCRL." (PMID 36547473, 2022). "Mutations in OCRL are responsible for Lowe syndrome and Dent 2 disease, which is an X-linked multi-systemic disorder that predominantly affects the eyes, kidney and CNS (Bökenkamp and Ludwig, 2016)." (PMID 35979861, 2022). "The results demonstrated truncating mutations of the OCRL gene were mostly seen in patients with Lowe syndrome than in Dent-2 disease, while mutation of the OCRL gene is more likely located at exon 2–12 in Dent-2 disease than that in Lowe syndrome." (PMID 35919034, 2022). "Disease-causing mutations occur throughout the OCRL gene in patients with Lowe syndrome, but mainly in exons 9–15, which encode the catalytic domain of the protein." (PMID 35919034, 2022). "Mutation in the inositol polyphosphate 5-phosphatase OCRL is known to cause disruption in endosomal trafficking and alterations in primary cilia assembly as observed in Dent disease and Lowe syndrome." (PMID 35378997, 2022). "Mutations affecting the OCRL gene were primarily associated with Lowe syndrome, and subsequently with Dent-2 disease." (PMID 35919034, 2022). "OCRL, whose mutations cause the rare genetic disorder Lowe syndrome, has been implicated in a number of cellular functions, including endocytic trafficking, cytokinesis, ciliogenesis, and lysosomal homeostasis." (PMID 35878408, 2022). "A large international study on OCRL variants recently widened the range of exons leading to the DD2 phenotype by demonstrating that mutations related to Lowe syndrome can be located among exons 8 and 24, while exons 4–15 are involved in DD2." (PMID 32860533, 2021). "Compared with ClC-5, fewer studies have been conducted on the OCRL functional changes caused by the pathogenic variants identified in patients with Lowe syndrome or DD2." (PMID 32860533, 2021).
Lowe syndrome (continued). "OCRL is a causative gene for Lowe syndrome and Dent-2 disease, in which fibroblasts present impaired ciliogenesis." (PMID 34414314, 2021). "Pathogenic variants in the OCRL gene are known to cause Lowe syndrome (LS) (MIM #309000 LS), while DD2 is frequently described as a mild form of LS." (PMID 34680992, 2021). "Mutations in OCRL cause Lowe syndrome and Dent disease, and INPP5E mutations occur in MORM and Joubert syndromes." (PMID 33119550, 2021). "Pathogenic variants of the OCRL gene were associated first with Lowe syndrome, and later with Dent disease (DD2)." (PMID 32860533, 2021). "We identified two novel OCRL mutations in two unrelated Chinese boys, each with a severe phenotype of Lowe syndrome." (PMID 34488756, 2021). "Patients carrying the same pathogenic OCRL variant have been diagnosed sometimes as having Lowe syndrome, sometimes as cases of DD2." (PMID 32860533, 2021). "Lowe oculocerebrorenal syndrome, a congenital disease characterized by low IQ, and defective kidney proximal tubule resorption, is caused by a defect in the OCRL gene." (PMID 35928786, 2021). "Both PHETA1 and PHETA2 have a C-terminal phenylalanine-histidine motif (F&H motif) that serves as a binding site for OCRL, encoded by a gene that is mutated in Lowe syndrome (MIM #309000)." (PMID 32152089, 2020). "Lowe syndrome and Dent-2 disease are caused by mutations in the OCRL gene, which encodes for an inositol 5-phosphatase." (PMID 31811534, 2020). "Next, we plan to analyze splicing abnormalities in the OCRL gene causing Lowe syndrome and in the GLA gene causing Fabry disease, using the same approach." (PMID 32201916, 2020). "Defective of the gene OCRL causes Lowe oculocerebrorenal syndrome, which is characterized by congenital cataracts, central hypotonia, mental retardation, and proximal renal tubular dysfunction." (PMID 33061794, 2020). "Defects in another phosphoinositide phosphatase, OCRL, are associated with a severe ciliopathy, oculocerebrorenal syndrome of Lowe." (PMID 32252387, 2020). "Lowe syndrome (LS) is caused by loss-of-function mutations in the X-linked gene OCRL, which codes for an inositol polyphosphate 5-phosphatase that plays a key role in endosome recycling, clathrin-coated pit formation, and actin polymerization." (PMID 32393163, 2020). "The oculocerebrorenal syndrome of Lowe, also known as Lowe syndrome, is a rare X-linked disorder caused by mutations in the OCRL gene, which encodes for a type II inositol polyphosphate 5-phosphatase." (PMID 31811534, 2020). "Mutations in OCRL are related to Lowe syndrome, a multisystem disorders affecting eyes, the nervous system, and kidney." (PMID 32244264, 2020). "OCRL is mutated in oculocerebrorenal syndrome of Lowe (Lowe syndrome) (OMIM #309000) and Dent 2 disease (OMIM #300555)." (PMID 32970140, 2020). "This overlap of clinical phenotypes between Lowe syndrome and Dent-2 disease is indicative of the heterogeneity of OCRL mutations." (PMID 31811534, 2020). "In this study, we present the first in vivo investigation of the functions of PHETA proteins, which are membrane adaptor proteins for the Lowe syndrome causative protein, OCRL." (PMID 32152089, 2020). "Point mutations in the OCRL gene cause the multisystemic disorder Lowe syndrome, affecting the eyes, kidneys, and the central nervous system." (PMID 31676009, 2019). "Point mutations in the OCRL gene cause Lowe syndrome and Dent disease, which are characterized as a multisystemic disorder." (PMID 31676009, 2019). "OCRL is mutated in Lowe syndrome and Dent-2 disease, rare X-linked conditions in which patients fibroblasts display shorter cilia." (PMID 31443299, 2019). "Other monogenic disorders of phosphoinositide metabolism include Lowe’s syndrome and Joubert syndrome, which can be caused by mutations in the inositol polyphosphate 5-phosphatases OCRL and INPP5E, respectively." (PMID 31034465, 2019).